NDEL1 (nudE neurodevelopment protein 1 like 1)
Diseases named in the same sentence as NDEL1 in open-access papers:
NDEL1 is named in the same sentence as 36 diseases in open-access papers, as found by Europe PMC text mining. Sharing a sentence is not in itself a finding about the gene and the disease. The quoted sentences say what the papers report.
schizophrenia (23 papers, 2009 to 2025). A major psychotic disorder characterized by abnormalities in the perception or expression of reality. "Understanding these Ndel1‐driven changes is crucial, providing valuable insights into the pathophysiology of neurodevelopmental and mental disorders linked to reduced Ndel1 activity, such as schizophrenia, autism, and bipolar disorder." (PMID 41432414, 2025). "Schizophrenia is associated with duplication or deletion of the gene locus containing Nde1 and Ndel1." (PMID 35493069, 2022). "Dysfunction of nuclear distribution element-like 1 (Ndel1) is associated with schizophrenia, a neuropsychiatric disorder characterized by cognitive impairment and with seizures as comorbidity." (PMID 33615226, 2021). "Polymorphisms in several genes encoding DISC1-interactors have been associated with schizophrenia, and altered hippocampal expression of NDEL1, FEZ1, and LIS1 has been detected in post-mortem brains of schizophrenic patients." (PMID 24940743, 2014). "Taken together, these results provide evidence that Ndel1 dysfunction may be important for the pathogenic mechanisms and manifestation of symptoms and/or comorbidities common to both epilepsy and schizophrenia." (PMID 33615226, 2021). "The protein binding interaction between Nde1, Ndel1, and DISC1 is well-established and the genetic interaction between Nde1/Ndel1 and DISC1 is associated with an increased risk for schizophrenia." (PMID 35493069, 2022). "The levels of DISC-1 and TDP-43, 2 molecules related to schizophrenia and amyotrophic lateral sclerosis–frontal temporal dementia were unchanged in both hippocampal and neocortical tissues of Ndel1 CKO mice when compared with those of WT littermates." (PMID 33615226, 2021). "Lower Ndel1 activity has been reported in the plasma of individuals with schizophrenia compared with healthy controls, particularly those with treatment-resistant schizophrenia." (PMID 28588507, 2017). "The oligopeptidase nuclear distribution E like-1 (Ndel1) modulates several neurodevelopmental processes involved in schizophrenia pathophysiology such as cell signaling, neurite outgrowth, neuronal migration, and cytoskeletal organization." (PMID 28588507, 2017). "Our study is the first to compare the peripheral blood expression of NDEL1 between patients and controls and is consistent with a previous study, which demonstrated reduced NDEL1 plasma activity in schizophrenia." (PMID 24940743, 2014). "A recent study reported evidence for NDEL1 and NDE1 association with schizophrenia in an American population." (PMID 19000741, 2009). "In this study, we further characterized the role for Ndel1 in mouse behaviors that may be relevant to clinical manifestations shared between schizophrenia and epilepsy." (PMID 33615226, 2021). "In the present study, a specific rat model for schizophrenia (SCZ) was used to evaluate the effects of a long-term treatment with typical or atypical antipsychotics on NDEL1 enzyme activity measured in the blood and selected brain regions of an animal model for SCZ and a control normal rat strain." (PMID 33116174, 2020). "Deficiency in Ndel1 results in embryonic lethality and postmortem studies and human genetic studies have implicated NDEL1 in several neuropsychiatric diseases such as schizophrenia, both emphasizing the importance of NDEL1 functions in brain development." (PMID 31815665, 2019). "Furthermore, emerging evidence of genetic association (NDEL1, PCM1, PDE4B) and copy number variation (NDE1) implicate several DISC1-binding partners as risk factors for schizophrenia in their own right." (PMID 21195721, 2012). "That both NDE1 and NDEL1 express multiple isoforms in the brain, self-associate, complex with each other and bind to DISC1 provides a mechanism for fine-tuning the respective roles of these schizophrenia-related proteins in the cell." (PMID 19000741, 2009).
schizophrenia (continued). "Moreover NDEL1 transcripts were reported to be reduced in the brains of schizophrenia patients compared to healthy controls." (PMID 19000741, 2009). "It has been proposed that aggresome formation may cause a loss of function of DISC1 by disrupting its interaction with partners, such as nuclear distribution element-like (NDEL1/NUDEL), or by impairing mitochondria transport and function, which may have a role in the pathogenesis of schizophrenia." (PMID 27462430, 2015). "We reported previously lower NDEL1 enzyme activity in blood of treated first episode psychosis and chronic schizophrenia (SCZ) compared to healthy control subjects, with even lower activity in treatment resistant chronic SCZ patients, implicating NDEL1 activity in SCZ." (PMID 33116174, 2020).
Lissencephaly (8 papers, 2008 to 2024). A spectrum of malformations of cortical development caused by insufficient neuronal migration that subsumes the terms agyria, pachygyria and subcortical band heterotopia. "In summary, we have identified the first two human lissencephaly patients caused by the de novo somatic variant p.R105P of NDEL1, a long-expected potential gene for cortical malformations." (PMID 38194050, 2024). "This study identifies the first lissencephaly-associated NDEL1 variant and sheds light on the distinct roles of NDE1 and NDEL1 in nucleokinesis and MCD pathogenesis." (PMID 38194050, 2024). "Ndel1 binds to Lis1, a causative gene product for lissencephaly, and Ndel1 and Lis1 cooperatively control cytoplasmic dynein functions." (PMID 23294285, 2013). "Although NDEL1 variants have never been reported to cause lissencephaly in humans, previous studies have strongly linked NDEL1 to other lissencephaly genes such as LIS1 and DYNC1H1, making NDEL1 a good candidate gene for lissencephaly." (PMID 38194050, 2024). "NDE1 and its homolog NDEL1 (Nuclear distribution protein nudE-like 1) physically interact with LIS1 (Lissencephaly 1), the first lissencephaly gene identified, and form a complex involved in neuronal proliferation, differentiation, and migration within the brain." (PMID 23637818, 2013). "However, several other proteins such as Ndel1, the partner of LIS1 involved in lissencephaly, ASPM involved in microcephaly, or spastin involved in hereditary spastic paraplegia, are also neuronal MAPs." (PMID 18782428, 2008).
mental disorder (7 papers, 2013 to 2025). A disease that has its basis in the disruption of mental process. "The oligopeptidase Ndel1 (NudE neurodevelopment protein 1 like 1) is a multifunctional protein implicated in neurodevelopmental processes, intensively investigated as a potential biomarker in psychiatric disorders." (PMID 41432414, 2025). "NDEL1 is also linked to the etiology of various mental illnesses and neurodegenerative disorders." (PMID 23861741, 2013). "Present data provides new insights in the role of NDEL1 and its possible interactions with neurotransmitter systems such as the dopaminergic pathway, and the potential liability of this pathway involving neuropeptides and neuropeptidases on susceptibility for severe mental disorders." (PMID 33116174, 2020). "A deeper understanding of the pathways modulated by this potential biomarker of neurodevelopment and pathological conditions of mental illness may help to pave the way for novel therapies needed for multiple debilitating brain disorders, also highlighting the Ndel1 roles in epilepsy." (PMID 41432414, 2025). "We have provided the most comprehensive documentation of the expression patterns of Nde1 and Ndel1 in cultured cells as well as in mouse and human brains, and also highlight that dosage effects of these two proteins might contribute to some cases of mental disorder." (PMID 24785679, 2014).
microcephaly (5 papers, 2008 to 2025). A congenital or acquired developmental disorder in which the circumference of the head is smaller than normal for the person's age and sex. "More recently, lower Ndel1 activity has also been associated with microcephaly induced by Zika virus infection during pregnancy." (PMID 41432414, 2025). "While the loss of function in NDE1 leads to microcephaly-related malformations of cortical development (MCDs), NDEL1 variants have not been detected in MCD patients." (PMID 38194050, 2024). "Notably, the link to microcephaly is particularly compelling, as this condition is often recognized as a cell‐cycle disorder resulting from neuronal progenitor cell‐cycle arrests, and the Ndel1 expression modulation was also confirmed by RNA‐seq." (PMID 41432414, 2025). "By preventing nuclear migration to the ventricular surface of the developing brain, we predicted that NDE1 knockdown, but not NDEL1 knockdown, would prevent RGP cells from dividing, identifying a potential NDE1-specific microcephaly mechanism." (PMID 27553190, 2016).
psychosis (4 papers, 2013 to 2020). "Particularly, myelin basic protein (MBP) and NudE neurodevelopment protein 1 like 1 (NDEL1) genes were upregulated in the first episode of psychosis, as compared with other groups, and were possibly related to the first molecular signs of SZ." (PMID 33020462, 2020). "In addition, MBP and NDEL1 expression levels were higher in both SCZ and BD patients than in healthy controls, indicating that these genes may be related to psychosis per se (independently of diagnosis)." (PMID 27701407, 2016). "Furthermore, MBP and NDEL1 expression levels were higher in SCZ and BD patients than in healthy controls, indicating that these genes are psychosis related (independent of diagnosis)." (PMID 27701407, 2016).
depression (3 papers, 2014 to 2021). "The levels of Ndel1 are also altered in human and models with epilepsy, a chronic condition whose hallmark feature is the occurrence of spontaneous recurrent seizures and is typically associated with comorbid conditions including learning and memory deficits, anxiety, and depression." (PMID 33615226, 2021). "Based on the classical interpretation of the forced swim task as a model of depression-like behavior, Ndel1 CKO are unlikely “depressive,” as they appear more active in this task." (PMID 33615226, 2021). "Moreover, a subgroup of FEP patients with depression showed lower levels of NDEL1 expression, opposite to our finding in BD, which is also at the opposite pole of depression." (PMID 27701407, 2016). "Similarly, cg04897932, which is hypomethylated in affected twins (Δβ = −.04, p = .0002), is located upstream of NDEL1, which forms a complex with DISC1, an established risk gene for several psychiatric conditions including major depression." (PMID 24929637, 2014). "Thus, higher NDEL1 expression might be characteristic of BD and FEP without depression, while lower NDEL1 expression levels could be associated to FEP with depression." (PMID 27701407, 2016).
epilepsy (3 papers, 2020 to 2025). A brain disorder characterized by episodes of abnormally increased neuronal discharge resulting in transient episodes of sensory or motor neurological dysfunction, or psychic dysfunction. "Our findings align with this literature, as the hippocampus was the brain region with the highest number of DAPs, and disease association analysis pointed to epilepsy, reinforcing Ndel1's crucial role in this condition, as suggested by others." (PMID 41432414, 2025). "In summary, the Ndel1 CKO mouse strain represents a complex model of epilepsy with multiple underlying molecular and cellular changes." (PMID 32864616, 2020). "Moreover, deficiency of Ndel1 has also been linked to increased susceptibility to convulsions and epilepsy, and the Ndel1cko mice manifest increased mortality as an epileptic phenotype." (PMID 41432414, 2025). "Thus, based on findings in this animal model, Ndel1 is implicated in postnatal epilepsy with potential contribution to adult epileptogenesis." (PMID 32864616, 2020). "An important question is whether Ndel1 is the only pertinent cytoskeletal target for adult epilepsy." (PMID 32864616, 2020). "Our study highlights the importance of Ndel1 in the manifestation of species-specific animal behaviors that may be relevant to our understanding of the clinical conditions shared between neuropsychiatric disorders and epilepsy." (PMID 33615226, 2021). "For example, the generation of tamoxifen-inducible Ndel1 KO mice to turn on and off Ndel1 expression in specific populations of hippocampal and/or cortical neurons in adulthood will allow us to understand in a spatio-temporal manner the involvement and plasticity of the cytoskeleton in epilepsy." (PMID 32864616, 2020).
glioma (2 papers, 2014 to 2016). A benign or malignant brain and spinal cord tumor that arises from glial cells (astrocytes, oligodendrocytes, ependymal cells). "Interestingly, NDE1 and NDEL1 have been found in gliomas and their expression is highly associated with the activity of glioma cell migration and proliferation." (PMID 24785679, 2014). "Although NDE1 and NDEL1 have been shown to be expressed in some human gliomas, their expression in normal astrocytes has not been well described." (PMID 24785679, 2014). "Additionally, although Nde1 regulates radial glial functions during development and its function is pivotal for human glioma formation, the astrocytic distribution of Nde1 and Ndel1 has not been investigated extensively." (PMID 24785679, 2014).
Pachygyria (2 papers, 2016 to 2024). Pachygyria is a malformation of cortical development with abnormally wide gyri with sulci 1,5-3 cm apart and abnormally thick cortex measuring more than 5 mm (radiological definition). "In this study, we identified two patients with pachygyria, with or without SBH, both carrying the same postzygotic mosaic pathogenic NDEL1 variant, p.R105P." (PMID 38194050, 2024). "Here, we identified two patients with pachygyria, with or without subcortical band heterotopia (SBH), carrying the same de novo somatic mosaic NDEL1 variant, p.Arg105Pro (p.R105P)." (PMID 38194050, 2024).
Anxiety (1 paper, 2021). Intense feelings of nervousness, tension, or panic often arise in response to interpersonal stresses. "Combined with the open field results and the reduced exploratory behavior observed in cages, we propose that the Ndel1 CKO may display anxiety-like behaviors." (PMID 33615226, 2021).
Charcot-Marie-Tooth disease (1 paper, 2011). An inherited degenerative disorder involving the peripheral nerves. "The findings that Ndel1 acts on the functions of intermediate filament protein NF-L and Dyn2 (this study), both mutated in the sensory motor neurodegenerative Charcot-Marie-Tooth disease further highlight his key role in degenerating neurons." (PMID 21283621, 2011).
lissencephaly type 1 (1 paper, 2018). "CENP-F has been implicated in dynein recruitment and regulation through a pathway involving Nde1, Ndel1, and Lis1, the product of the lissencephaly type 1 gene (77, –, 79, 90, 91)." (PMID 29748388, 2018).
neuroblastoma (1 paper, 2011). Neuroblastoma (NB) is the most common solid, extracranial childhood tumor. "The association between Ndel1 and Dyn2 was also detected in neuroblastoma CAD cells, rat primary cultured hippocampal neurons and adult mouse cortex." (PMID 21283621, 2011).
osteosarcoma (1 paper, 2023). A usually aggressive malignant bone-forming mesenchymal neoplasm, predominantly affecting adolescents and young adults. "Of note, 0.28% of all splicing events, such as ES in NDEL1 and ACIN1, exhibited osteosarcoma specificity but also patient heterogeneity." (PMID 37457661, 2023).
ovarian carcinoma (1 paper, 2023). A malignant neoplasm originating from the surface ovarian epithelium. "Bioinformatics prediction unveiled a close association of GPR137, NDEL1, DYNC1H1, and TUBA1A with ovarian cancer development and prognosis." (PMID 38021163, 2023). "Further, multiple gene correlation analyses revealed a significant positive linear relationship between GPR137 expression in ovarian cancer tissues and the expression levels of NDEL1, DYNC1H1, and TUBA1A." (PMID 38021163, 2023). "Moreover, by examining clinical data, we found that the expression of four genes, GPR137, NDEL1, DYNC1H1, and TUBA1A, differed significantly between tumor tissues and normal tissues, and their expression levels were significantly associated with poor prognosis of ovarian cancer patients." (PMID 38021163, 2023). "The findings of the study indicate that ovarian cancer patients with elevated expression of GPR137, NDEL1, and TUBA1A genes experienced a statistically significant increase in survival time, as demonstrated by Kaplan-Meier survival analysis." (PMID 38021163, 2023). "Thus, the findings of the analysis indicate a significant correlation of the expression levels of GPR137, NDEL1, DYNC1H1, and TUBA1A with the advancement and prognosis of ovarian cancer." (PMID 38021163, 2023).
status epilepticus (1 paper, 2025). Status epilepticus is defined as a continuous seizure lasting more than 30 min, or two or more seizures without full recovery of consciousness between any of them. "Conversely, Ndel1 is upregulated in the hippocampus following status epilepticus (SE), suggesting a potential role for Ndel1 in the pathophysiology of the spontaneous seizure." (PMID 41432414, 2025).
neurological disorders (4 papers, 2013 to 2025). "We recently reported that insulin-dependent inhibition of GSK3β, a kinase with a growing list of neurologic disease links, phosphorylates dynein and regulates its interactions with Ndel1 and APC." (PMID 29404402, 2018).
neurodevelopmental disorder (3 papers, 2016 to 2021). A behavioral and cognitive disorder with onset during the developmental period that involves impaired or aberrant development of intellectual, motor, or social functions. "Nuclear distribution element-like 1 (Ndel1) plays pivotal roles in diverse biological processes and is implicated in the pathogenesis of multiple neurodevelopmental disorders." (PMID 27546710, 2016). "Harnessing the biology of NDEL1 S336/S332 phosphorylation or the TARA-DYRK2-GSK3β signaling module will provide new insights toward the discovery of novel components and pathways that are pertinent to brain development and neurodevelopmental disorders." (PMID 31815665, 2019).
brain disorder (1 paper, 2025). A disease affecting the brain or part of the brain. "Ultimately, this research may contribute to a deeper understanding of Ndel1's role not only in brain development, but also in its neural plasticity and function at early developmental phase, clarifying how this enzyme could contribute to the etiology of psychiatric and other brain disorders." (PMID 41432414, 2025).
mitochondrial disease (1 paper, 2022). "Our data point to cargo specificity in NDEL1 function and raise the possibility that defects in the LIS1/NDEL1 dynein regulatory pathway could contribute to mitochondrial diseases with axonal pathologies." (PMID 35465088, 2022).
NDEL1 also shares sentences with these, for which no sentence is quoted: bipolar disorder (4 papers); tumor (2); amyotrophic lateral sclerosis (1); autism (1); band heterotopia (1); cancer (1); Cerebral ischemia (1); Cognitive impairment (1); developmental delay (1); glioblastoma (1); hereditary spastic paraplegia (1); high grade glioma (1); ischemia (1); Macrocephaly (1); Miller-Dieker syndrome (1); neuronal migration disorder (1).